LY75-CD302 (LY75-CD302 readthrough)
Synonyms: gp200-MR6
Gene: Protein-coding gene on chromosome 2 (159,771,851 to 159,904,710, reverse strand). Ensembl gene ENSG00000248672.
Genetic constraint (gnomAD): Loss-of-function variants: 196 observed, 244.59 expected, observed/expected ratio (o/e) 0.8, 90% interval 0.71 to 0.9. The upper end of that interval is the gene's LOEUF score, 0.9, which puts it in group 3 of 6, group 1 being the genes least tolerant of losing a copy. Missense variants: 2,049 observed, 2,208.2 expected, observed/expected ratio (o/e) 0.93, 90% interval 0.89 to 0.96. Synonymous variants: 680 observed, 748.38 expected, observed/expected ratio (o/e) 0.91, 90% interval 0.85 to 0.97.